PTH1R (parathyroid hormone 1 receptor)
Diseases named in the same sentence as PTH1R in open-access papers (continued):
Sharing a sentence is not in itself a finding about the gene and the disease.
tumor (32 papers, 2017 to 2025). "The expressions of PTHrP and PTH1R in LALSCC were associated with the degree of tumor differentiation (p = 0.01 and 0.04, respectively)." (PMID 35761298, 2022). "The analysis of data regarding the expressions of PTHrP and PTH1R showed an association with the degree of tumor differentiation." (PMID 35761298, 2022). "The results of our study are consistent with those reported by previous studies, where we observe that increased expression of the PTH1R correlated with an advanced tumor grade 3 and elevated mortality risk." (PMID 33316777, 2020). "In needle aspirates of bone metastases, Pth1r expression was decreased compared with the 4T1-derived primary tumor." (PMID 36692956, 2023). "The roles of PTHrP/PTH1R signaling in cancer progression, metastasis, and tumor dormancy are context-dependent." (PMID 37046642, 2023). "Tumor-derived PTHrP circulates and triggers PTH1R on osteoblasts, leading to the expression of VEGF-A and IL6." (PMID 37085481, 2023). "Our identification of PTH1R as a hub gene further supports its role in forming a tumor microenvironment in bone." (PMID 38435029, 2023). "In this manuscript, we further delved into the molecular mechanism of PTH1R-dependent MDSC mobilization in tumor hosts using in vitro cell binding assays, in vivo models and human breast cancer patient-derived MDSCs." (PMID 37085481, 2023). "The presence of Pth1r, however, was critical in both the tumor and the bone for the inhibitory actions of PTH on skeletal metastasis." (PMID 36692956, 2023). "Gene changes with PTH treatment in the tumor–bone microenvironment is abolished with PTH1R knockdown in 4T1 cells." (PMID 36692956, 2023). "The response of PTHrP/PTH1R target cells, including cancer cells and different cells in the tumor microenvironments, can differ depending on the stage of disease progression." (PMID 37046642, 2023). "In conclusion, this study analyzes for the first time the patterns of PTHrP and PTH1R expression in LALSCC in relation to tumor histology and grade." (PMID 35761298, 2022). "Taken together, these results suggested that CALCR and PTH1R played a critical role in tumor immune escape, which was involved in the carcinogenesis of GC." (PMID 35252217, 2021). "Despite the importance of PTHLH tumorigenic role, our knowledge of the PTH1R that mediate changes in the tumor progression and interaction with PTHLH in ICC is still limited." (PMID 29178939, 2017). "The CellPhoneDB analysis showed active interactions between pericytes and other cell types, particularly with other stromal cells The pathways exhibiting enrichment in the interaction between PTH1R+ pericytes and tumor cells/ECs were of particular interest to us." (PMID 39640361, 2024). "Our results, based on analyses of available microarray data sets, demonstrated that expression levels of Pth1r in primary tumors were significantly lower than in healthy breast tissue and that tumor progression was often accompanied by a significant reduction in Pth1r levels." (PMID 36692956, 2023). "In addition to the functional activation of MDSCs, we observed that PTHrP rapidly increases MDSCs in the circulation of tumor hosts, suggesting that osteoblastic PTH1R activation potentially contributes to the expansion and/or mobilization of MDSCs." (PMID 37085481, 2023). "These inhibitory effects were lost when PTH1R signaling was perturbed either in tumor or bone." (PMID 36692956, 2023). "Patients with poorly differentiated tumors, transglottic tumor site, PTHrP positive and PTH1R negative tumors showed a significantly increased risk of relapse." (PMID 35761298, 2022). "The role of PTH1R in tumor progression is still poorly understood." (PMID 35203352, 2022).
tumor (continued). "A significant relationship was found between tumor PTHrP and PTH1R expression and patient survival." (PMID 35761298, 2022). "Therefore, the interplay of PTH1R and CaSR acts in concert to evoke excessive bone destruction and progressive tumor growth." (PMID 30151009, 2018). "Understanding the interplay between PTH1R and CaSR signaling in the development of BrCa bone metastases could lead to a novel therapeutic approach to control both osteolysis and tumor burden in the bone." (PMID 30151009, 2018). "The potential interplay between the PTH1R and FAK signaling pathways has been illuminated in tumor research." (PMID 40890141, 2025). "The FN1–aVb1 and FN1–a5b1 pairs exhibited a high level of enrichment in the interaction between PTH1R+ pericytes and ECs, with FN1–aVb1 also showing significant enrichment between PTH1R+ pericytes and tumor cells." (PMID 39640361, 2024). "PTH1R activation by parathyroid hormone (PTH) or PTH-related peptide (PTHrP), a tumor-derived counterpart, mobilized monocytic (M-) MDSCs from murine BM without increasing immunosuppressive activity." (PMID 37085481, 2023). "It has also been proposed that PTHrP may promote tumor-induced angiogenesis by increasing expression of pro-angiogenic factors such as vascular endothelial growth factor and Factor VIII, or via PTH1R activation and cAMP signaling." (PMID 37358786, 2023). "Genetic knockdown of Pth1r in primary O.S. cells reduced proliferation, invasion, and the expression of RANKL in vitro and profoundly inhibited O.S. tumor growth, but increased differentiation/mineralization of the O.S. tumor cells in vivo." (PMID 37046642, 2023). "In contrast, treatment with anti-PTH1R antibody did not prevent the induction of milk protein gene expression or STAT5 activation in tumor cells, demonstrating that the PTH1R is not required for PTHrP to trigger secretory differentiation in tumors." (PMID 35440032, 2022). "Third, reducing PTH1R expression in tumor cells does not alter tumor growth or secretory differentiation of the tumor cells, demonstrating that tumor expression of the PTH1R is not required for the observed phenotype." (PMID 35440032, 2022). "Because of its nuclear localization sequence, PTHrP can also act as an intracrine factor to promote tumor proliferation that is independent of PTH1R and then augment bone turnover, thereby driving the bone-tumor vicious cycle." (PMID 30151009, 2018). "Moreover, the mean expected survival probability of patients with PTHrP positive and PTH1R negative tumor phenotype was significantly lower than that of patients with both PTHrP and PTH1R positive tumor phenotype." (PMID 35761298, 2022). "In addition, neither ablating the Type 1 PTH/PTHrP receptor (PTH1R) in epithelial cells nor treating Tet-PTHrP;PyMT mice with an anti-PTH1R antibody prevented secretory differentiation or altered tumor latency." (PMID 35440032, 2022). "In LALSCC nuclear PTHrP and absence of PTH1R expressions could be useful in predicting response and/or resistance to cetuximab in combined therapies, contributing to an aggressive behavior of tumor cells downstream to HER1." (PMID 35761298, 2022). "Furthermore, since PTHrP is up-regulated by HER1 and contributes to tumor malignancy downstream to HER1, we investigated if the expression of PTHrP and PTH1R could be prognostic and/or predictive biomarkers of sensitivity/resistance to bio-radiotherapy with cetuximab." (PMID 35761298, 2022). "Overall, these results suggest a conflicting role for the presence or absence of the PTH1R in cancer and metastasis, but its presence is critically important for the biological actions PTH in changing the tumor microenvironment." (PMID 36692956, 2023).
cancer (20 papers, 2016 to 2024). A tumor composed of atypical neoplastic, often pleomorphic cells that invade other tissues. "Cancer cells release PTHrP, which binds to PTH1R in stromal cells or osteoblasts and causes RANKL production." (PMID 38435029, 2023). "PTHLH/PTH1R signaling is aberrantly induced or activated in different cancer types and is associated with poor prognosis." (PMID 29178939, 2017). "This review aims to contribute to the current knowledge of PTHrP/PTH1R in cancer by summarizing the existing literature on the topic and identifying knowledge gaps and future directions for research." (PMID 37046642, 2023). "By assessing the strengths and limitations of these studies, we aim to shed light on the potential for targeting PTHrP/PTH1R in cancer for better efficacy and eventual translation into clinical practice." (PMID 37046642, 2023). "We expect that successful development of these novel reagents will significantly advance the understanding of the context-dependent roles of PTHrP/PTH1R, and eventually translate to the clinic to target PTHrP/PTH1R in cancer and metastasis." (PMID 37046642, 2023). "While PTH1R mediates the major actions of PTHrP, the role of PTH1R in cancer and the effectiveness of blocking it have been studied less, compared to PTHrP, partially because of its significant role in bone." (PMID 37046642, 2023). "We expect that successful developments of these novel reagents will significantly advance the understanding of the context-dependent roles of PTHrP/PTH1R, and eventually translate to the clinic to target PTHrP/PTH1R in cancer and metastasis." (PMID 37046642, 2023). "Nevertheless, the efficacy of blocking PTHrP and PTH1R has been shown in various types of cancer, suggesting its potential for therapeutic applications." (PMID 37046642, 2023). "The impact of parathyroid hormone-related protein (PTHrP) and parathyroid hormone receptor 1 (PTH1R or PTHR1) on cancer initiation, growth, and metastasis has been extensively documented in a number of in vitro and in vivo studies." (PMID 37046642, 2023). "At the cellular level, PTH1R promotes the proliferation, survival, and differentiation of a variety of cells, including osteoblasts, chondrocytes, osteocytes, and some cancer cells." (PMID 35265269, 2022). "Studies from different research groups have reported that the decreased expression of PTH1R was a poor prognosis factor in multiple types of cancer." (PMID 34660292, 2021). "Further, graph centrality measures suggested the importance of upregulated genes such as BIRC5, UBE2C, BUB1B, KIF20A and PTH1R in cancer." (PMID 34728699, 2021). "While genes such as PTH1R, DPT, DES, TCF21 and PDE2A are downregulated in many cancers, cell cycle associated genes, centromere proteins and kinesin family proteins are upregulated in all the cancer types we studied." (PMID 34728699, 2021). "PTH and PTHrP, which signal through the same receptor Pth1r, induce adipose tissue and muscle wasting in murine models of cancer and CKD31,33." (PMID 34302016, 2021). "However, these upstream regulators have broad and significant roles in cancer and metastasis beyond PTHrP/PTH1R signaling, raising concerns about the specificity of the inhibitions." (PMID 37046642, 2023). "In addition to directly inhibiting PTHrP or PTH1R, other approaches have been explored in cancers, including targeting upstream regulators of the PTHrP expression." (PMID 37046642, 2023). "However, inhibiting the Wnt pathway in cancer and metastasis is a complex challenge that goes beyond PTHrP/PTH1R signaling." (PMID 37046642, 2023). "These authors found that m6A targets parathyroid hormone receptor-1 mRNA and that Mettl3 depletion impairs Pth1r mRNA translation, providing clues about the role of RNA-methylation on estrogen signaling in women’s cancer." (PMID 31426393, 2019).
cancer (continued). "Cancer cells are one source of PTHrP, which causes humoral hypercalcemia and promotes the osteolytic bone metastases of a malignancy by activating the type 1 PTH/PTHrP receptor (PTH1R) in the kidneys and skeleton." (PMID 30115896, 2018). "Based on our findings, further investigation for interfering with PTH1R, which mediate signaling in cancer cells, may serve as effective treatment approaches to ICC patients." (PMID 29178939, 2017). "Parathyroid hormone (PTH)/Pth1r, TGF-β/SMAD, WNT and other signaling pathways are modulated by m6A marks, which are essential in the cellular differentiation and cancer development." (PMID 36527141, 2022). "For example, Parathyroid Hormone 1 Receptor (PTH1R) and collagen-binding Dermatopontin (DPT) were downregulated in all the 18 cancers." (PMID 34728699, 2021). "Coupled with the upregulation of PTH1R (parathyroid hormone type 1 receptor) seen in our mouse models, PTHLH likely plays a significant role in cancer cell proliferation, migration, and invasion." (PMID 32290096, 2020). "Despite these findings, the attempts to target PTHrP/PTH1R signaling in cancer therapy have not produced successful results in the clinical setting." (PMID 37046642, 2023). "On the other hand, in cancer and CKD the role of the PTHrP/PTH1R axis has also been studied, showing that PTH and PTHrP, through the PTH1R receptor, cause the ‘browning’ of white adipose tissue plus energy production via the activation of uncoupling protein-1 (UCP-1)." (PMID 34827568, 2021). "In line with our observations, the downregulation of PTH1R and DPT could be important for most of the cancers." (PMID 34728699, 2021). "Thus, the patients with cancer with high expression of CALCR and low expression of PTH1R may benefit from immunotherapy." (PMID 35252217, 2021). "Collectively, these data indicate that a fraction of M-MDSCs bound to the endosteal surface in the bone marrow are mobilized by PTH1R activation in osteoblasts, which potentially is not the only mechanism for M-MDSC mobilization in cancer patients." (PMID 37085481, 2023).
skeletal dysplasia (4 papers, 2011 to 2025). Any Mendelian diseases that affects growth and development of the skeleton. "In this article, we identified a novel missense mutation in PTH1R with differential phenotypes in tooth development, facial features, and skeletal dysplasia." (PMID 37840415, 2023). "Mutations in the parathyroid hormone receptor PTH1R can be seen in skeletal dysplasias such as Murk Jansen metaphyseal chondrodysplasis, Blomstrand chondrodysplasia, Eiken skeletal dysplasias and primary failure of tooth eruption but thus far are not linked to parathyroid adenomas or carcinomas." (PMID 21747852, 2011). "In addition, mutations in PTH1R cause skeletal dysplasia and severe growth retardation." (PMID 37840415, 2023).
autosomal recessive disease (1 paper, 2022). Autosomal recessive form of disease. "These diseases are both caused by mutations in the PTH/PTHrP receptor, PTH1R, but JMC is an autosomal dominant disorder that results from constitutive activation of the PTH1R receptor, whereas BOCD is an autosomal recessive disease that leads to loss-of-function of PTH1R." (PMID 36726589, 2022).
endocrine disorder (1 paper, 2022). "iPPSD1 is associated with PTH1R variants and variable phenotypes including ossification anomalies and primary failure of tooth eruption but no endocrine disorder." (PMID 35846276, 2022).
infection (1 paper, 2008). The state of being infected such as from the introduction of a foreign agent such as serum, vaccine, antigenic substance or organism. "However, following infection with HTLV-1 there was a marked induction of PTH1R in PBMCs." (PMID 18541021, 2008).
PTH1R also shares sentences with these, for which no sentence is quoted: Enchondromatosis (3 papers); Maffucci syndrome (3); autosomal dominant disease (2); hepatocellular carcinoma (2); melanoma (2); metaphyseal chondrodysplasia (2); Obesity (2); Osteopenia (2); Pseudohypoparathyroidism type I‐b (2); Skeletal diseases (2); vitamin D deficiency (2); acrodysostosis (1); adrenocortical cancer (1); bone metastasis (1); coronary artery disease (1); cutaneous melanoma (1); disc degeneration (1); ductal carcinoma in situ (1); dysplastic coxarthrosis (1); entropion (1); gastric neuroendocrine tumors (1); gestational diabetes (1); Gynecomastia (1); hypophosphatemia (1); hypophosphatemic rickets (1); inflammatory bone diseases (1); Insulin resistance (1); invasive ductal breast carcinoma (1); kidney disease (1); larynx cancer (1).
A further 18 diseases each share a sentence with PTH1R in 1 paper.